CD4 (CD4 molecule)
Diseases named in the same sentence as CD4 in open-access papers (continued):
Sharing a sentence is not in itself a finding about the gene and the disease.
infection (continued). "HIV is a devastating infection, which weakens the body's ability to fight other infections by attacking the body's immune system, specifically the white blood cells called CD4 cells." (PMID 35252102, 2022). "We first examined, within the HIV-infected cultures, the infection rates among CD4+ Tm cells expressing high vs. low levels of AOL or WGA." (PMID 35787792, 2022). "However, direct infection of ex vivo generated susceptible cells, such as pre-stimulated CD4 T cells or immortalized T cell lines, may bias outcomes in favor of the direct viral cytopathic effects that have been known to induce apoptosis in infected cells (3, –, 7)." (PMID 36000842, 2022). "Gene therapy experiments in the SIV/macaque model have indeed demonstrated that protection of a limited subset of CD4 + T cells from infection is sufficient to maintain a broader CD4 + T cell population through bystander effect." (PMID 35082297, 2022). "We showed homosubtypic protection associated with pre-existing CD4 and CD8 T cell responses, against infections in H3N2 epidemics." (PMID 35858844, 2022). "Yet, even almost one year post-infection Long COVID patients exhibit significantly altered proportions of Tregs within the CD4+ T cell population." (PMID 36582234, 2022). "The mRNA vaccines, however, yielded higher frequencies of cytokine positive CD4+ T cells compared to the Astra Zeneca vaccine and the naturally occurred infections." (PMID 35468147, 2022). "Infection with SARS-CoV-2 generates CD4+ and CD8+ T cell responses detectable by IFN-γ production that expand over 7 days in vitro with SARS-CoV-2 S peptide stimulation." (PMID 36271095, 2022). "Vhl cKO mice showed a high frequency of CD44 + CD62L + central memory CD8T cells (TCM) in lungs before and during infection, while CD4 TCM were only increased in Vhl cKO at 8 weeks after infection." (PMID 36064840, 2022). "After adjusting for target CD4+ T cell density in B cell follicles and extrafollicular areas, preferential infection of CD4+ cells in B cell follicle is even more pronounced in humans living with HIV and SIV-infected rhesus macaques." (PMID 36505432, 2022). "Immediately following infection, CD4 T cell counts fall steeply, recover partially, and then settle within a few weeks/months to a value smaller than in the pre-infection state." (PMID 35271687, 2022). "Given the fact that IFN-γ suppresses Cryptosporidium infection and controls parasite replication, it has been described that CD4+ T cells are also essential for parasite elimination and the establishment of an effective immune response following infection." (PMID 36211380, 2022). "Virus (hepatitis C virus and HIV) infection and replication have been reported to increase carbohydrate and lipid metabolism in infected CD4+ T cells." (PMID 35805143, 2022). "Intranasal infection with JKD6159-gD resulted in gDT-2 CD4+ T cell activation predominately within the mLN, these cells where then released into the circulation and by day 7 p.i gDT-2 CD4+ T cells were detectable in both the lung and nasal tissue." (PMID 35637249, 2022). "We found that PD-L1 was upregulated on macrophages and CD11b+ CD103- dendritic cells following infection, correlating with the observed upregulation of PD-1 on CD4+ T cells." (PMID 36265003, 2022). "Upon P. berghei challenge infection, proliferations of germinal center B cells in the inguinal lymph nodes, as well as blood CD4+ and CD8+ T cells were induced." (PMID 36140395, 2022). "Macrophages are among one of the first cell types to be infected by HIV-1 upon primary infection, acting as reservoirs for infection and intermediate cells that transmit the infection to CD4+ T cells." (PMID 36146843, 2022). "Although MSM tend to be diagnosed earlier than HET, the differences in RT/F between the groups are seen also in CD4 counts at seroconversion, which would occur at similar times post infection in the two groups." (PMID 35271687, 2022).
infection (continued). "While the CD8 T cell-depleted mice succumbing to infection had a trend of lower organ and serum titers than the CD4 T cell-depleted counterparts, only the kidney showed significant differences between all three groups." (PMID 36289695, 2022). "Representative plots reveal that challenge infection with the 50 LD50 T. gondii ME49 enhanced CD4+ and CD8+ T cell populations by roughly 30% and 12%, respectively." (PMID 35214611, 2022). "P&S induced significantly higher levels of lung-resident antigen-specific CD4+ T cells that phenotypically resemble infection-induced CD4+ T cells (IV-CD45−tetramer+CD69+CD4+)." (PMID 36302057, 2022). "The produced immune adaptive response is similar in both natural infection and vaccination, even if a slight advantage, in terms of frequencies of spike specific and polyfunctionality of CD4+ T cells, was observed after the administration of mRNA-1273." (PMID 36012246, 2022). "HIV infection impairs intestinal mucosal immunity from the early phase of infection via a profound depletion of mucosal CD4 + T cells." (PMID 35197986, 2022). "CCR5 is also the primary coreceptor for the human immunodeficiency viruses (HIVs), supporting its entry into CD4+ T lymphocytes upon transmission and in the early stages of infection in humans." (PMID 35154162, 2022). "Only after spontaneous (reference patient HH-20-225) and treatment-induced (index patient HH-20-044) resolution and control of the infection did the proportion of CD127+ virus-specific CD4+ T-cells increase to the levels of the bulk CD4+ T-cells." (PMID 35746736, 2022). "FMT from l-arginine-treated mice caused significant increases in IFN-γ-producing CD4+CD44+ T cell and CD4+CD44+ T cell populations in the cervical lymph nodes compared to control mice during Mabc infection." (PMID 35579969, 2022). "It appeared that IL-6 deficiency in B cells leads to a general down-regulation of the ifng gene expression in the lung and a decreased frequency of mycobacteria-specific CD4+IFN-γ+ T cells at the early stage of infection." (PMID 35154093, 2022). "HIV-1 spreads between CD4+ T cells via two distinct mechanisms: either by cell-free infection or by direct cell-to-cell transmission." (PMID 35062333, 2022). "In a mouse model of oropharyngeal candidiasis (OPC), after resting for 6 weeks following primary infection, the memory CD4+ conferred immunity to secondary infection by producing antigen-specific IL-17A responses." (PMID 36177012, 2022). "Experienced mice that had CD4+ cell depletion during initial rounds of infection exhibited significantly less AM numbers compared with control experienced mice." (PMID 35133985, 2022). "Thus, the decline in the number of pDCs and CD1c+ mDCs in patients with KD and their immature phenotype and the increase in TIM-3 expression on CD4+ T cells suggested a deficiency in the defensive system of patients with KD and may account for a high infection rate in these patients." (PMID 35222381, 2022). "Additionally, a limited similarity between the CD4+ epitopes identified in vaccinated and naturally infected donors may be due to the differences of the measles virus strain used for vaccination and the strain that caused natural infection." (PMID 35336928, 2022). "ABR analysis revealed that CD4/CD8 T cell-depleted mice surviving ML29 infection had a significant increase in their auditory threshold." (PMID 36289695, 2022). "Despite diminished CD4+ T cell capacity at 8 and 14 weeks post-infection, α-GC+KEX1 elicited robust titers in both animals." (PMID 36561749, 2022). "The lower initial CD4 levels in the erratic subset suggest that the infection has progressed further in the pretreatment phase." (PMID 35485581, 2022). "Infection of resting CD4+ target T cells by cell-to-cell spread was preferentially detected in CD45RA− resting memory T cell populations rather than CD45RA+ naive T cells, which are both abundant in peripheral blood." (PMID 35417711, 2022).
infection (continued). "Chemokines, such as CCL5, recruit CD4 T cells to sites of infection, where cytokines, such as IL-12 produced by DCs initiate the differentiation of CD4 T cells towards a Th1 subtype, producing IL-2 and IFN-γ." (PMID 36211447, 2022). "At seven months post infection frequencies and numbers of M2-17+ CD4+ Tem were increased in MLNs and ILNs whereas only the number of M2-17+ CD4+ Tem was increased in spleen." (PMID 36275685, 2022). "Every fold increase in pre-existing seasonal H1N1 influenza A virus (sH1N1)-specific CD4 and CD8 T cells was associated with 28% (95% CI 11%, 41%) and 22% (95% CI 8%, 33%) lower pH1N1 infection odds, respectively." (PMID 35858844, 2022). "Following infection with herpes simplex virus or contact sensitization, CD4+ and CD8+ TRM cells colocalize nearby hair follicles." (PMID 36153349, 2022). "These CD4 T cells can persist for >6 months after infection and are still capable of producing IFN-γ in response to HSV reactivation and release from intraepidermal sensory axons." (PMID 36211447, 2022). "CD4+ T cells are indirectly involved in clearing infection by modulating the activity of other immune cells, including macrophages (Mø), neutrophils, B cells and CTLs." (PMID 35359994, 2022). "Systemic immune activation—assessed on circulating CD8+ or CD4+ T-cells by the co-expression of HLA-DR and CD38—is a hallmark of HIV and TB infections and correlates with more rapid HIV disease progression." (PMID 36145465, 2022). "Here, we attempt to elucidate the role of the CD4+ T cell response against infection with Tpp in PLWH." (PMID 36291681, 2022). "The development of viral neutralizing antibodies following infection has been associated with an increased abundance of Th1-like CD8+ and CD4+ cells, circulating CD4+ T follicular helper cells (cTfh), and activated T cells." (PMID 35710908, 2022). "After the ex vivo infection of CD4+ T cells, we observed higher expression of the CD32 molecule in comparison to uninfected cells." (PMID 35616530, 2022). "The role of CD4+ T-cells in viral clearance is noteworthy; the number and function of CD4+ T-cells were impaired in HCV positive patients compared to HCV patients who resolved the infection." (PMID 35267563, 2022). "After infection, these antigen-specific CD4+ T cells were present in high proportions in the airways." (PMID 36211412, 2022). "Collectively, these data demonstrate that cell-to-cell spread drives productive infection of resting CD4+ T cells that have the capacity to disseminate infection." (PMID 35417711, 2022). "M2e or NA-specific IgG antibody production in mLN, IFN-γ secreting cells, and IFN-γ+CD4+ T cells in lungs were observed at higher levels in aged mice with m-cNA-M2e VLP vaccination compared to mock control at day 6 after A/Phil infection." (PMID 36006890, 2022). "In the earlier phase of infection when blood CD4+ T cell levels are above 200 per μl, the leptomeninges are the most conspicuous location of chronic CNS HIV-1 infection so that a clinically silent aseptic meningitis is frequent." (PMID 35775044, 2022). "We found that they are crucial for infection and differentiation of Tregs, since an increased number of CD4+/FoxP3+CD25+ cells was found in the spleens of infected mice and their depletion abrogated the Treg expansion induced by the infection." (PMID 36271272, 2022). "These early reports were confirmed subsequently by multiple studies, demonstrating the establishment of latency in resting CD4 T cells via infection by cell-free virus particles as well as cell-to-cell transmission." (PMID 35895672, 2022). "This analysis suggests that the LN microenvironment impedes the process of CD4+ T cell activation in the later stage of the infection (week 8)." (PMID 36317628, 2022). "In particular, patients with subtype D infections show a faster rate of CD4+ T cell decline than that in patients infected with subtype B." (PMID 36312730, 2022).
infection (continued). "The increase in CD4+IFNγ+ T cells and the decrease in CD4+IL-4+ T cells observed at the site of infection correlated with decreased parasite burden in the lesion of Mrp8;Metfl/fl mice." (PMID 35041723, 2022). "Infection by the members of the MTBC induces increased migration of CD4+ and CD8+ T lymphocytes to the infected organs." (PMID 35456728, 2022). "Historically, a robust CD4+ and CD8+ T-cell response during early infection has been associated with recovery from LF." (PMID 37034031, 2022). "During these months, the newly introduced antiretroviral regimen controlled the infection well, the viremia remained undetectable, the cluster of differentiation number (CD4) was 1277 cells/mm3, and the CD4/CD8 ratio was 1.48." (PMID 36553155, 2022). "We have reported modulations on the expression of the four cell markers in Mtb-specific CD4+ T-cells, dependent on the presence of clinical disease or infection alone, and that also reflect therapy efficacy." (PMID 35935194, 2022). "At 28 days post infection (d.p.i.), Cd4E4mΔ/Δ/ E4aΔ/Δ mice had significantly lower frequency and number of Tbet+CD11ahiCD44+ helper T cells in the dLNs compared with CD4+/+ controls." (PMID 35304452, 2022). "At approximately 14–21 dpi, the reactivation of MDV in CD4+ T cells initiates a late phase of cytolysis and immunosuppression, and thus, the second cytolytic infection occurs." (PMID 36680047, 2022). "In the same study, after infection with Yersinia ruckeri, CD4+ T lymphocytes generated equivalent levels of cytokines relevant to Th1, Th17, and regulatory T cells, and CD4+ monocyte/macrophage populations had high phagocytic capacity." (PMID 37073166, 2022). "Cultures were then infected with HIV-F4.HSA, and CD4+ T cell infection rates were assessed 3 d later by flow cytometry." (PMID 36016345, 2022). "Specifically, during infection, CD4+ T lymphocytes can be activated by toll-like receptor signaling pathways." (PMID 36703972, 2022). "Clonal full-length env genes derived from viruses of individuals in these distinct clinical groups were analyzed for expression, CD4 dependent-Env-mediated fusion, cell-to-cell viral transfer, and infection efficiency." (PMID 35401460, 2022). "Prior to dissemination and latency, HIV-1 establishes infection by a single viral particle infecting a single cell, mainly a CD4+ T cell." (PMID 35215997, 2022). "At the acute infection stage, the virus rapidly propagates, the virus content in each milliliter of blood can reach millions, and CD4 count will also decrease significantly." (PMID 35205215, 2022). "We provided further evidence that a high proportion of children who seroconverted to SARS-CoV-2 were able to mount specific CD4+ T cell responses, that were still detectable up to over 100 days after infection." (PMID 35911689, 2022). "After infection, a large number of parasitic-specific IgA are produced, and the CD4+ T cell response is helpful for the production of IgA and the control of infection." (PMID 36428376, 2022). "Spike S1 subunit-specific IFNγ and tumour necrosis factor (TNF) production and S2-specific TNF responses in CD4+ T cells were higher in previously infected individuals than in infection-naive individuals." (PMID 34778853, 2022). "FOXP4 is a transcription factor expressed in both thymocytes and peripheral CD4+ and CD8+ T cells, and is necessary for normal T cell cytokine recall responses to antigen following pathogenic infection." (PMID 36531218, 2022). "coli was significantly lower than group NOB-uninfected at 24 and 72 h post-infection (p < 0.05), the percentage of CD4+T cells in group NOB-E." (PMID 35720836, 2022). "In stark contrast, in Mtb-LT1 infection, IL-17 expressing CD4+ T cells increased and were significantly higher in comparison to Mtb-HT1 infection." (PMID 35173157, 2022). "The average distribution of all CD4+ T cell subsets was similar in the different conditions, with a decrease in Temra cells in the IL-15 condition after infection." (PMID 35499323, 2022).
infection (continued). "Results from a study analyzing donors from different backgrounds suggested that the nature and type of infection leading to CD4 CTL formation shapes the molecular profile of the resulting CD4 CTL." (PMID 35903098, 2022). "HTLV-1 shares transmission routes with Human Immunodeficiency virus (HIV); moreover, the two retroviruses have a common in vivo tropism, since CD4+ T-cells are their major targets of infection." (PMID 35867643, 2022). "We have also previously shown that early CD4+ T cell responses can predict RBD-specific memory B cell frequencies at 1-year post-infection." (PMID 36544780, 2022). "Methanol extracts of all tested fungi, A. alternata showed a weak HIV-1 inhibition of less than 50 ng/ml in CD4+ T cells after infection." (PMID 36583026, 2022). "The CD4+ T cells of patients who cleared the infection had higher CD25 and Human leukocyte antigen (HLA)-DR expression." (PMID 36555623, 2022). "We next performed bivariate and multivariable Cox regression analyses of pre-infection plasma cytokines and time to CD4 decline below 500 cells/μl prior to ART initiation." (PMID 35165387, 2022). "By contrast, when CD4 T cells were depleted from WT mice by administration of anti-CD4 mAb prior to the challenge infection we observed significant reduction in survival in immunized mice." (PMID 35260804, 2022). "When B10.S mice, expressing the alternate MHC class II I-As molecule, were sampled post infection, and CD4 T cells were purified and tested, reactivity to HA-A, NP, NA, and NS1 was apparent." (PMID 35215193, 2022). "Our findings that B. burgdorferi infection leads to increased PD-1 expression on CD4+ T cells suggests there is some degree of impairment to the T cell compartment during infection." (PMID 36265003, 2022). "The total HIV DNA levels obtained by qPCR (ranging from 260 to 41,000 copies per 106 CD4+ T cells) were much higher than the infection frequency of proviruses obtained with the FLIPS assay." (PMID 35916523, 2022). "We identify that partially or fully-vaccinated transplant recipients after infection with Omicron BA.1 have the greatest BA.1 neutralizing antibody and BA.1-specific polyfunctional CD4+ and CD8+ T-cell responses, with potent cross-neutralization against BA." (PMID 35927279, 2022). "Together, data obtained here in CC patients and in the mouse experimental model point to the heart as an important target-organ for CD4+ T cells with cytolytic potential generated in response to infection with T. cruzi." (PMID 35670567, 2022). "These included NK1.1−Vα8β4+CD4+ T cells in the draining lymph node as well as keratinocytes, neutrophils and eosinophils at the dermal site of infection." (PMID 35894051, 2022). "Although not dramatic, the expression of the exhaustion marker CTLA-4 on AIM+ CD4+ T cells in the infection-only group was elevated by 1.29-fold compared with that in the hybrid-immunity group within 1–6 months post vaccination." (PMID 36494338, 2022). "Infections with both T151A and R304M significantly increased the levels of IL-2, IL-17, TNF-β, and CD8 in brain and thymus, IFN-γ in thymus, and CD4 in brain, as compared to infection with the rPS parental backbone virus (P<0.05)." (PMID 36016955, 2022). "Relative to their WGALow counterparts, the WGAHigh cells also preferentially expressed higher levels of CD4 and the HIV co-receptor CCR5, potentially explaining the increased susceptibility of these cells to infection." (PMID 35787792, 2022). "There was a significant (p < 0.05) decrease in CD4+ T cell 1 week post-infection, which later on increased significantly (p < 0.05) after 7 weeks in mice infected with M. s_Rv1515c." (PMID 35813825, 2022). "Infectivity of all viruses is first normalized to infection of cells with a high density of CD4 (CD4/high+CCR5/high)." (PMID 35975998, 2022). "This was in contrast to previous data with the virulent Armenia strain of the virus, where elevated numbers of CD4+CD8α cells were observed five days post-infection." (PMID 35891467, 2022).